ENDOG (endonuclease G)
Diseases named in the same sentence as ENDOG in open-access papers (continued):
Sharing a sentence is not in itself a finding about the gene and the disease.
depression (1 paper, 2023). "All SNPs of EXOG and ENDOG modulated the risk of depression, but the strongest effect was observed for rs1065800, while rs9838614 and rs2977998 indicate that they might influence the severity of symptoms, and, to a lesser extent, treatment effectiveness." (PMID 37834200, 2023). "Several unique results were obtained only in early onset depression: alleles of EXOG c.-188T > G (rs9838614) modulated its risk, while the C/C genotype of ENDOG c.-220C > T (rs2997922) had a protective effect." (PMID 37834200, 2023). "According to the best of our knowledge, this paper is the first to report that SNPs located in genes encoding proteins maintaining mitochondrial genome integrity, i.e., EXOG, POLG and ENDOG, affect the incidence, onset, severity and treatment of depression." (PMID 37834200, 2023). "Analysis revealed that the haplotypes of both genes influenced the incidence of depression: TG and GA of EXOG and CC of ENDOG had a protective effect, while TT of EXOG and CT and TT of ENDOG significantly increased the OR of an episode occurrence." (PMID 37834200, 2023).
endometrial adenocarcinoma (1 paper, 2021). "ENDOG expression was directly correlated with AKT phosphorylation and inversely correlated with PTEN expression in a set of three endometrial adenocarcinoma cell lines." (PMID 34359707, 2021).
endometrial neoplasm (1 paper, 2021). Tumors or cancer of ENDOMETRIUM, the mucous lining of the UTERUS. "Noteworthy, ENDOG deficiency reduced proliferation of endometrial tumor cells expressing low PTEN/high p-AKT levels, and Endog deletion blunted the growth of PTEN-deficient 3D endometrial cultures." (PMID 34359707, 2021). "Taking into account the existing correlation between ENDOG expression and PTEN mutations, these results are also suggestive of a possible cooperation between both genes in the oncogenic transformation on some subsets of endometrial neoplasms." (PMID 34359707, 2021).
hepatoma (1 paper, 2021). "Consistently, in other hepatoma cell lines, knockdown of ENDOG increased phosphorylation of mTOR and ULK1, as well as suppressed autophagy under starvation." (PMID 33473107, 2021).
kidney injury (1 paper, 2021). Trauma to the kidney. "In acute kidney injury induced by cisplatin, EndoG could be induced only in DNase I–expressing wild‐type mice, while DNase I knockouts did not have EndoG induction in the kidney." (PMID 34085765, 2021).
lung diseases (1 paper, 2019). "The finding of increased nuclear translocation of AIF and EndoG in HBE cells from smokers compared to non-smokers suggests it may play a role in smoke-related lung diseases." (PMID 31396404, 2019).
melanoma (1 paper, 2017). A malignant, usually aggressive tumor composed of atypical, neoplastic melanocytes. "Results of Annexin V/PI staining of melanoma cells, character of activation of caspase 3, PARP, MAPK, and EndoG protein, and the morphological changes suggest induction of apoptosis in Les-3833-treated cells." (PMID 28409496, 2017). "Results of Annexin V/PI staining of melanoma cells and activation of caspase 3, PARP, MAPK, and EndoG protein suggest apoptosis in Les-3833-treated cells." (PMID 28409496, 2017). "Interestingly, the doxorubicin did not affect the level of the EndoG protein in treated melanoma cells that suggested different mechanism of action of Les-3833 and doxorubicin in these tumor cells." (PMID 28409496, 2017).
monocytic leukemia (1 paper, 2018). "In conclusion, our findings demonstrate that WSPIS exhibits a growth retardation effect on human monocytic leukemia cell lines in vitro through cell cycle progression delay and induction of endoG-mediated apoptotic cell death." (PMID 29382173, 2018).
nonalcoholic fatty liver disease (1 paper, 2023). "Taken together, we demonstrate that loss of ENDOG suppresses acetyl-CoA production and lipid synthesis, along with reducing endoplasmic reticulum stress, which eventually alleviates high-fat diet-induced nonalcoholic fatty liver disease in female mice." (PMID 37794041, 2023).
ovarian carcinoma (1 paper, 2023). A malignant neoplasm originating from the surface ovarian epithelium. "In ovarian cancer (OC), however, EndoG is upregulated and nuclear‐localized due to elevated reactive oxygen species (ROS) and plays a proliferative function." (PMID 36734593, 2023). "Here, we report that endonuclease G, which exhibits altered expression in ovarian cancer, does not function as a cell death effector that digests chromosomal DNA in ovarian cancer." (PMID 36734593, 2023).
pancreatitis (1 paper, 2018). Inflammation of the pancreas. "These alternative pathways seem to be mediated by mitochondrial factors, like apoptosis-inducing factor (AIF), endonuclease G (endoG), and so forth, but it is not yet clarified if these pathways are involved in pancreatitis pathogenesis." (PMID 29686719, 2018).
prostate tumor (1 paper, 2019). "We interpret these results to show that Apt63 binds preferentially to breast and prostate tumor cells that express its plasma membrane target, and that Apt63 induces cell death upon binding, through a mechanism that involves release and nuclear translocation of endoG." (PMID 31006104, 2019).
sarcopenia (1 paper, 2014). Progressive decline in muscle mass due to aging which results in decreased functional capacity of muscles. "Another important protein that may contribute to sarcopenia is endonuclease G (EndoG)." (PMID 25097722, 2014).
tongue cancer (1 paper, 2020). A malignant neoplasm affecting the tongue. "It has also been shown to regulate apoptosis-associated proteins by increasing the expression of the anti-apoptotic protein B-cell lymphoma 2 and decreasing levels of the pro-apoptotic protein Bcl-2-associated X protein, apoptosis-inducing factors, and endonuclease G in tongue cancer cells." (PMID 32219334, 2020).
cancer (22 papers, 2013 to 2026). A tumor composed of atypical neoplastic, often pleomorphic cells that invade other tissues. "In this study, we demonstrated that nuclear translocation of EndoG causes DNA damage and phosphorylation of Src on Tyr416, contributing to oncogenic transformation and cancer stemness." (PMID 38977663, 2024). "Eleostearic acid hindered cancer cell proliferation, induced apoptosis, caused mitochondrial membrane potential loss, provoked apoptosis-inducing factor and endonuclease G nuclear translocation, as well as arrested the cancer cell cycle." (PMID 37240264, 2023). "ENDOG, a nuclear-encoded endonuclease, affects cancer cell viability and tumor prognosis via the PI3K/PTEN axis." (PMID 34992654, 2021). "The impact of caspase-3 activation in maintaining the stemness of both normal cells and cancer cells aligns with our current study, wherein caspases activation induces EndoG nuclear translocation, resulting in DNA damage in transforming cells." (PMID 38977663, 2024). "During the two decades since EndoG was shown to be a cell death effector in C. elegans and mice, most studies have focused on inducing EndoG activity to kill cancer cells or blocking its activity to induce cytoprotection." (PMID 36734593, 2023). "In vivo, in vitro and in silico experiments show that Endog/ENDOG silencing blunts proliferation of tumor cells dependent on high p-AKT/low PTEN activity and that ENDOG has prognostic value in specific cancer types." (PMID 34359707, 2021). "Western blot analysis showed clear spontaneous EndoG translocation into the nucleus from the mitochondria in various cancer cells." (PMID 28337983, 2017). "We found that Bid knockdown is sufficient to attenuate Bak oligomerization; the release of Cyt c, AIF, and endoG; and caspase-3 cleavage in cancer cells." (PMID 26469967, 2015). "Furthermore, the co-immunoprecipitation results suggest that AIF interacts with ENDOG within the nucleus of treated, target cancer cells." (PMID 40227697, 2025). "Regarding cancer cell death, studies have collectively suggested that increasing ROS levels might be a possible strategy to destroy cancer cells via nuclear EndoG activity because oxidative stress would induce EndoG expression and translocation to the nucleus." (PMID 36734593, 2023). "We propose that targeting EndoG, either by itself or in combination with platinum‐type agents, might be a promising strategy to enhance cancer cell death in the treatment of OC patients." (PMID 36734593, 2023). "Therefore, we decided to assess the effects of silencing ENDOG expression on the proliferation of cancer cell lines and to determine its relationship with the levels of p-AKT expression." (PMID 34359707, 2021). "Since, changes in 5hmC mtDNA methylation are associated with a wide range of pathological conditions such as cancer, neurodegeneration and aging, our observations broaden the current understanding of the development of these diseases and highlight EndoG as a potential target for future therapies." (PMID 29719607, 2018). "We next analyzed EndoG location in various normal and cancer cells." (PMID 28337983, 2017). "Additionally, downstream caspase-3 reinforces Bak activation and the release of AIF and endoG through positive loops, which sensitize cancer cells to the treatment with genistein." (PMID 28352215, 2017). "Furthermore, elevated EndoG levels can sensitize cancer cells to chemotherapeutic drugs." (PMID 36734593, 2023). "Another requirement for the caspase-independent apoptosis of cancer cells is the upregulated expression and translocation of apoptosis-inducing factor (AIF) and endonuclease G (EndoG)." (PMID 36081952, 2022).
cancer (continued). "In summary, our results show that reducing ENDOG expression hinders growth of some tumors characterized by low PTEN activity and high p-AKT expression and that ENDOG has prognostic value for some cancer types." (PMID 34359707, 2021). "To obtain direct evidence that spDSBs enhance the tumorigenic abilities of host cancer cells, we evaluated MDA-MB-231 cells with EndoG and/or CAD knockout." (PMID 28337983, 2017). "A non-apoptotic function of caspase-3 in cancer is revealed that oncogene-driven malignant transformation is aided by caspase-3 activation via a pathway involving Endonuclease G (EndoG)." (PMID 41514679, 2026). "Surface ATP5B also appears to be important as a tumor-specific survival factor: cancer cells expressing ecto-ATP5B were rapidly killed by Apt63 binding, undergoing nuclear translocation of endonuclease G and DNA fragmentation, while adjacent normal tissues were spared." (PMID 31006104, 2019). "It is not clear how EndoG is regulated in normal cells if cancer cells are an extreme example." (PMID 36734593, 2023). "While exploring a novel function of EndoG in various cancer types, we noticed that EndoG might not be involved in cell death in OC cells." (PMID 36734593, 2023). "Besides, MS13 treatment in DU 145 and PC-3 cells has shown the downregulation of PPP3CB, TFDP1, SMAD3, and ENDOG, which the anti-cancer activity have not been reported in PCa but noted in other cancers." (PMID 34366863, 2021).
tumor (19 papers, 2013 to 2025). "Caspase-3 activity appears to be a major regulator of EndoG’s nuclear translocation, as evidenced by reduced nuclear EndoG expression in caspase-3-deficiency mPOR-derived tumor samples." (PMID 38977663, 2024). "In contrast to the potent tumor-forming abilities of mPOR-transduced control cells, putative transformed cells with EndoG deficiency exhibited significantly attenuated tumor-forming capabilities, with prolonged survival of syngeneic hosts." (PMID 38977663, 2024). "Immunohistochemistry staining of tumor samples from caspase-3- or EndoG-deficient xenografts further confirmed the relationship between caspase-3/EndoG and pSTAT3 expression, which is consistent to the phosphorylation of Src at Tyr416." (PMID 38977663, 2024). "Importantly, tumor samples from PyMT transgenic mice with caspase-3 deficiency exhibited minimal EndoG nuclear translocation." (PMID 38977663, 2024). "Interestingly, when ENDOG-deficient IK cells were subcutaneously injected in the hind limbs of immune-deficient Prkdcscid mice, tumor growth was significantly reduced compared to control IK cells." (PMID 34359707, 2021). "Indeed, we show that ENDOG/Endog gene silencing reduces tumor cell proliferation in association with decreased p-AKT abundance and downregulation of the downstream signaling pathway." (PMID 34359707, 2021). "However, some important differences have been observed in the processes altered by ENDOG deficiency in tumor cells compared to those observed previously." (PMID 34359707, 2021). "Western blot analysis indicated that caspase-3/EndoG knockout significantly reduced the level of phosphorylated STAT3 at Y705 (pSTAT3) in mPOR-transformed cells as well as in tumor samples from Casp3WT;Pymt and Casp3KO;Pymt mice." (PMID 38977663, 2024). "Mitochondria, through the microfluidic device, released endonuclease G (Endo G) into adjacent tumor cells, which we referred to herein as unsealed mitochondria." (PMID 37206227, 2023). "We show that this mitochondrial transfer process released endonuclease G (Endo G) into tumor cells, which we referred to herein as unsealed mitochondria." (PMID 36289539, 2022). "Because ENDOG silencing reduced proliferation of IK cells, a PTEN-deficient tumor cell line, we decided to further explore this event." (PMID 34359707, 2021). "Analysis of the contribution of ENDOG expression to cell proliferation in diverse tumor cell lines with different status of the PTEN/p-AKT pathway further demonstrated that ENDOG silencing targets p-AKT-dependent signaling to reduce cell proliferation." (PMID 34359707, 2021). "Here, we investigated the effect of ENDOG/Endog expression on proliferation in different tumor models." (PMID 34359707, 2021). "On the contrary, our results demonstrate that ENDOG gene silencing only influences proliferation in the tumor cell lines with the highest p-AKT abundance, which correlates with low or absent PTEN expression." (PMID 34359707, 2021). "The identification of the mitochondrial events regulated by ENDOG that impact AKT phosphorylation in tumor cells deserves further investigation." (PMID 34359707, 2021). "The results presented here show that reducing ENDOG expression in human tumor cell lines with low PTEN expression and high p-AKT abundance restrains cell proliferation." (PMID 34359707, 2021). "Functionally, binding of Apt63 to the plasma membrane exerts selective tumor cell killing by inducing translocation of endonuclease G from mitochondria to nucleus, DNA fragmentation, and apoptosis." (PMID 31006104, 2019). "PLK1 is overexpressed in HCC samples relative to normal controls, and its knockdown can induce apoptosis of tumor cells via the endonuclease-G pathway." (PMID 30705088, 2019).
tumor (continued). "A single intravenous injection of Apt63 induced rapid, tumor cell-selective binding and cytotoxicity in MDA-MB-231 xenograft tumors, associated with endonuclease G nuclear translocation and DNA fragmentation." (PMID 31006104, 2019). "In this context, we decided to investigate the potential role of ENDOG in tumor cell proliferation using different in vitro and in vivo cellular models and its potential clinical impact in CLL, which has an activated PI3K-PKB/AKT pathway in relation with their PTEN status." (PMID 34359707, 2021). "Interestingly, the overexpression of EndoG is important for the development of tumor progression, and the silencing of the EndoG gene contributes to the suppression of the proliferation of tumor cells." (PMID 34830126, 2021). "The absence of a functional G1/S checkpoint could explain the differences observed in cell cycle in the analyzed tumor cells compared to somatic cells that accumulate in G1 after ENDOG expression silencing." (PMID 34359707, 2021). "CLL is a frequent mature B-cell lymphoid neoplasm, where PI3K kinase is constitutively activated through BCR signaling, and may be an interesting tumor model to explore the possible clinical impact of ENDOG expression, either alone or in relation to PTEN status." (PMID 34359707, 2021). "Therefore, in the cell lines tested, the effects of ENDOG silencing on cell proliferation occurred in tumor cells with the highest p-AKT and low PTEN, except for the U87 GBM cell line, pointing to the existence of additional factors determining the impact of ENDOG on proliferation." (PMID 34359707, 2021). "These experiments therefore provide direct evidence that spDSBs induced by apoptotic nucleases EndoG and CAD play important roles in maintaining the tumorigenic abilities of the tumor cells." (PMID 28337983, 2017). "Upregulation of the anti-apoptotic genes BCL2L2, BAG3, and downregulation of pro-apoptotic genes DAXX, FAF1, PAK1, DFFA, ENDOG was found in reprogrammed tumours pointing to a cell cycle arrest without engagement of the apoptotic pathway." (PMID 29662623, 2018).
infection (9 papers, 2012 to 2025). The state of being infected such as from the introduction of a foreign agent such as serum, vaccine, antigenic substance or organism. "The results presented in this study indentify the activation of Bid-AIF/ EndoG as a novel mechanism by which pathogenic Leptospira species induce apoptosis in macrophages during an infection." (PMID 29184851, 2017). "ENDOG has been reported to be released from mitochondria under specific stresses, such as infection, genotoxicity, and starvation." (PMID 37794041, 2023). "Our previous study showed that AIF and/or EndoG was released from macrophage mitochondria during a leptospire-infection." (PMID 29184851, 2017). "Taken together, the results presented in our study showed that AIF and/or EndoG mediate the mitochondrion-related apoptosis of macrophages during infection with Leptospira species." (PMID 29184851, 2017). "When Bid was knocked down by siRNA, the release and nuclear translocation of AIF and EndoG, the ratio of DNA fragmentation and apoptosis were significant decreased during the infection." (PMID 29184851, 2017). "Nevertheless, PCD related genes that were up-regulated included metacaspase, endonuclease G, and cytochrome C, and these could still be identified in Pyr. yezoensis transcripts during infection." (PMID 31783543, 2019). "Therefore, in this study we investigated the signaling pathway of AIF and EndoG resulting in apoptosis of macrophages during infection with L. interrogans serovar Lai strain Lai." (PMID 29184851, 2017). "Our previous studies showed that the mitochondria in leptospire-infected J774A.1 cells are morphologically disrupted and that AIF and/or EndoG could be released from mitochondrion during leptospire-infection." (PMID 29184851, 2017). "Endonuclease G (Endo-G), an apoptotic nuclease, was up-regulated after RGNNV infection in SSN-1 cells, and was supposed to be involved in cell apoptosis induced by RGNNV." (PMID 36016359, 2022). "However, no activation of caspase-9 and mitochondrial release of CytC was observed during an infection, while AIF and/or EndoG showed translocation from the mitochondria to the cytosol." (PMID 29184851, 2017). "In addition, we also found that caspase-8 was activated during the infection, and in the caspase-8 inhibited macrophages, the ratio of apoptosis, the cleavage of Bid, and the release of AIF and EndoG from mitochondria were significantly decreased." (PMID 29184851, 2017).